IGKV1D-22 (immunoglobulin kappa variable 1D-22 (pseudogene))
Synonyms: A9; IGKV1D22
Gene: Immunoglobulin variable (V) pseudogene on chromosome 2 (90,010,741 to 90,011,184, forward strand). Ensembl gene ENSG00000253365.
Diseases named in the same sentence as IGKV1D-22 in open-access papers:
IGKV1D-22 is named in the same sentence as 189 diseases in open-access papers, as found by Europe PMC text mining. Sharing a sentence is not in itself a finding about the gene and the disease.
IGKV1D-22 shares sentences with these, for which no sentence is quoted: tumor (95 papers); cancer (59); infection (30); breast carcinoma (27); Sepsis (21); melanoma (18); rheumatoid arthritis (16); COVID-19 (15); colon carcinoma (13); myocardial infarction (11); autoimmune disease (10); cardiovascular diseases (10); psoriasis (10); pancreatic cancer (9); Arthritis (8); gastric cancer (8); atherosclerosis (7); colitis (6); diabetes (6); heart failure (6); Hyperglycemia (6); inflammatory bowel disease (6); renal fibrosis (6); asthma (5); immune disorder (5); lung carcinoma (5); myocardial ischemia (5); Obesity (5); acute respiratory distress syndrome (4); colorectal cancer (4).
A further 159 diseases each share a sentence with IGKV1D-22 in 4 papers or fewer.